PINX1 (PIN2 (TERF1) interacting telomerase inhibitor 1 )
Diseases named in the same sentence as PINX1 in open-access papers (continued):
Sharing a sentence is not in itself a finding about the gene and the disease.
tumor (continued). "Notably, PinX1 expression is diminished in HBV-related HCC, a reduction that facilitates tumor growth and enhances tumorigenic potential." (PMID 41383743, 2025). "We also provided evidence that deletion may decrease mRNA expression of PINX1 and MSRA, which are the other two tumor suppressor candidates located on del8p23.1." (PMID 40699642, 2025). "PINX1 (PIN2/TRF1-interacting telomerase inhibitor 1) was initially identified as an interacting protein of TRF1 in the telomeric shelterin complex and recognized as a potent intrinsic telomerase inhibitor, hence considered a tumor suppressor." (PMID 39174499, 2024). "PINX1 (Pin2/TRF1 interacting protein X1, an intrinsic telomerase inhibitor and putative tumor suppressor gene) may represent a novel prognostic tumor biomarker." (PMID 30079348, 2018). "The disruption of the PinX1/NPM interaction may help to prevent telomerase activation and telomere maintenance and subsequently suppress the growth of certain tumor cell types." (PMID 28255170, 2017). "Further correlation analyses demonstrated that negative expression of PinX1 in our UCB cohort was significantly associated with advanced N classification, higher proliferation index, and tumor multiplicity." (PMID 24268029, 2013). "PinX1 may play important roles in NPC proliferation, migration and apoptosis and has application potential in tumor-targeted gene therapy." (PMID 22316341, 2012). "PinX1 was upregulated in CRC tumor tissues compared with non-tumorous colorectal tissues." (PMID 40639785, 2025). "The mechanism of PinX1 functioning in tumor cells has not been fully elucidated." (PMID 22316341, 2012). "However, the biological function of PinX1 on UCB tumorigenesis and tumor progression has not been characterized." (PMID 24268029, 2013).
adenocarcinoma (3 papers, 2014 to 2017). A common cancer characterized by the presence of malignant glandular cells. "Among all cases, PinX1 positivity was found to be more frequent in SCC (36 of 101 samples) than in adenocarcinoma (5 of 55 samples), suggesting that PinX1 expression may be associated with specific tissue types." (PMID 28815183, 2017). "In addition, the expression of PinX1 protein was examined by IHC on a TMA including 40 adenocarcinoma and 8 normal prostate tissues." (PMID 24936151, 2014).
PINX1 also shares sentences with these, for which no sentence is quoted: medulloblastoma (3 papers); diabetes mellitus (2); endocervical adenocarcinoma (2); systemic lupus erythematosus (2); thyroid cancer (2); acne (1); acute promyelocytic leukemia (1); Burkitt lymphoma (1); Cirrhosis (1); colorectal adenocarcinoma (1); esophageal cancer (1); head and neck squamous cell carcinoma (1); Insulin resistance (1); lung squamous cell carcinoma (1); lymphoma (1); metastasis (1); ovarian serous cystadenocarcinoma (1); rectum adenocarcinoma (1); squamous carcinoma (1); systemic sclerosis (1); type 1 diabetes mellitus (1); type II diabetes (1).